Y_RNA (Y RNA )
Gene: Miscellaneous RNA gene on chromosome 1 (32,286,452 to 32,286,561, reverse strand). Ensembl gene ENSG00000252450.
Homologues: Orthologues: guinea pig Y_RNA (60% identical). Paralogues in human: Y_RNA (65% identical), Y_RNA (62% identical), Y_RNA (61% identical), Y_RNA (60% identical), RNY3P4 (59% identical), Y_RNA (59% identical), Y_RNA (58% identical), RNY3 (57% identical), RNY3P14 (57% identical), Y_RNA (57% identical), RNY3P10 (56% identical), RNY3P16 (56% identical), and 79 more.